USP35 (ubiquitin specific peptidase 35)
Diseases named in the same sentence as USP35 in open-access papers (continued):
Sharing a sentence is not in itself a finding about the gene and the disease.
breast carcinoma (5 papers, 2007 to 2023). "We uncovered that higher expression of deubiquitinase USP35, located in 11q14.1, was associated with ER+ breast cancer and poor survival." (PMID 34131114, 2021). "In the current study, we uncovered that higher USP35 expression is associated with ER+ breast cancer and poor prognosis." (PMID 34131114, 2021). "In summary, our study reveals that higher USP35 expression is associated with ER+ breast cancer and poor prognosis." (PMID 34131114, 2021). "Because higher USP35 expression is associated with ER+ breast cancer, we tested the hypothesis that ERα may be involved in regulating USP35 expression." (PMID 34131114, 2021). "USP35 may be a treatment target for ER+ breast cancer with endocrine resistance or with PIK3CA mutations or hyperactivation of the PI3K pathway." (PMID 34131114, 2021). "In addition, breast cancer with high USP35 expression or gene amplification is associated with poor survival." (PMID 34131114, 2021). "Given that USP35 expression is associated with ER+ breast cancer, we further investigated whether changes in USP35 levels affect the response of ER+ breast cancer cells to the commonly used drugs in endocrine therapies." (PMID 34131114, 2021). "Therefore, a putative small molecule inhibitor for USP35 may help overcome resistance to therapy with PI3K α inhibitor for ER+ breast cancer with PIK3CA mutations or hyper-activation of the PI3K pathway in the future." (PMID 34131114, 2021). "For example, USP35 promotes tumorigenesis in estrogen receptor (ER)-positive breast cancer by stabilizing and activating estrogen receptor α (Erα) to increases Erα transcriptional activity." (PMID 36864055, 2023). "Our study clearly demonstrated that USP35 promotes the growth of ER+ breast cancer cells in vitro and in vivo, which is consistent with higher USP35 expression in breast tumors compared with adjacent normal breast tissues." (PMID 34131114, 2021). "Our data support a model that estradiol promotes USP35 expression by downregulating miR-26a-5p and miR-140-3p in ER+ breast cancer cells." (PMID 34131114, 2021). "Knockdown of USP35 strongly decreased, whereas overexpression of USP35 increased ERα protein level in ER+ breast cancer cell lines (MCF-7 and ZR-75-1)." (PMID 34131114, 2021). "Since USP35 promotes ERα stability, our data indicate that USP35 forms a positive feedback loop with ERα, promoting tumorigenesis of ER+ breast cancer." (PMID 34131114, 2021). "Next, USP35 was overexpressed and knocked down using two different USP35 shRNAs in these ER+ breast cancer cells." (PMID 34131114, 2021). "To explore the function of USP35 in ER+ breast cancer, we first examined USP35 protein levels in different types of breast cancer cell lines." (PMID 34131114, 2021). "USP35 promoted the growth of ER+ breast cancer in vitro and in vivo, and reduced the sensitivity of ER+ breast cancer cells to endocrine therapies such as tamoxifen and fulvestrant." (PMID 34131114, 2021). "USP35 should be a potential therapeutic target for ER+ breast cancer that develops resistance to standard targeted therapies." (PMID 34131114, 2021). "USP35 promotes tumorigenesis of ER+ breast cancer by enhancing the stability and transcriptional activity of ERα, and increases resistance of ER+ breast cancer cells to endocrine therapy." (PMID 34131114, 2021). "USP35 promotes the growth of ER+ breast cancer cells by regulating the G1 to S phase transition, which is in agreement with USP35 being a cell-cycle regulator in mitosis." (PMID 34131114, 2021). "Because an amplicon in 11q14.1 containing USP35 was found in a small subset of breast cancer, we first analyzed USP35 expression in breast cancer cohort in publicly available databases, such as TCGA and METABRIC." (PMID 34131114, 2021). "Our results strongly suggest that PIK3CA mutants can signal to USP35 through AKT phosphorylating Ser613 to promote the growth of ER+ breast cancer cells." (PMID 34131114, 2021).
breast carcinoma (continued). "Immunoblotting analysis revealed that USP35 protein level was enhanced significantly after estradiol (E2) treatment in three different ER+ breast cancer cell lines." (PMID 34131114, 2021). "Our data indicate that USP35 and ERα form a positive feedback loop in promoting the growth of ER+ breast cancer." (PMID 34131114, 2021). "Our study demonstrated that USP35 is the bona fide target for miR-140-3p and miR-26-5p in ER+ breast cancer cells." (PMID 34131114, 2021). "Functionally, Ser613 phosphorylation was important for USP35 promoting E2-stimulated gene expression and enhancing the growth of ER+ breast cancer cells." (PMID 34131114, 2021). "Our study uncovers a novel mechanism by which USP35 interacts with and promotes the stability and the transcriptional activity of ERα, resulting in the growth of ER+ breast cancer cells." (PMID 34131114, 2021). "Statistical analysis showed that USP35 expression was positively correlated with miR let-7a level in breast cancer tissues (P < 0.05)." (PMID 26348204, 2015). "AKT phosphorylation of USP35 is critical for USP35′s action in ER+ breast cancer cells." (PMID 34131114, 2021). "Importantly, USP35 promotes the growth of ER+ breast cancer in vitro and in vivo, and reduces the response to endocrine therapies by enhancing the stability and transcriptional activity of ERα." (PMID 34131114, 2021). "In addition, Gene Set Enrichment Analysis (GSEA) also revealed that breast cancer with USP35-high expression was enriched in ESR1 up and luminal B up breast cancer." (PMID 34131114, 2021). "AKT may phosphorylate other protein target that acts in concert with USP35 to promote the expression of ERα target genes in ER+ breast cancer cells." (PMID 34131114, 2021). "Importantly, USP35 mRNA levels were higher in luminal (ER+) than in other subtypes of breast cancer." (PMID 34131114, 2021). "Considering the important role of ERα in ER+ breast cancer, we investigated whether USP35 regulates the ERα protein level." (PMID 34131114, 2021). "Furthermore, phosphorylation of Ser613 in USP35 by AKT, an effector of PI3K, is critical for USP35 nuclear translocation and promoting ERα transcriptional activity and the growth of ER+ breast cancer cells." (PMID 34131114, 2021). "There is a subgroup of ER+ with high level of USP35 mRNA, which maybe the result of USP35 amplification, since USP35 was amplified in ~13% of ER+ breast cancer." (PMID 34131114, 2021). "USP35 mRNA was overexpressed in primary breast carcinomas compared with adjacent normal tissues." (PMID 34131114, 2021). "Furthermore, Kaplan–Meier analysis showed that breast cancer with higher USP35 mRNA level exhibited significantly shorter overall survival time than those with lower mRNA level." (PMID 34131114, 2021). "Importantly, our data showed that estrogen increases USP35 protein expression by downregulating miR-140-3p and miR-26a-5p levels in ER+ breast cancer cells." (PMID 34131114, 2021). "In addition, AKT, a key effector of PI3K, phosphorylated USP35 at Serine613, which promoted USP35 nuclear translocation, ERα transcriptional activity, and the growth of ER+ breast cancer cells." (PMID 34131114, 2021). "Moreover, AKT-activated USP35 enhanced ERα stability by interacting and deubiquitinating ERα, suggesting that USP35 may be a therapeutical vulnerability for ER+ breast cancer with endocrine resistance." (PMID 36357379, 2022). "Furthermore, knockdown of USP35 also increased ERα ubiquitination in ER+ breast cancer cells." (PMID 34131114, 2021). "However, the role of USP35 in breast cancer is still unknown." (PMID 34131114, 2021). "USP35 protein levels were higher in commonly used ER+ (i.e., MCF-7, ZR-75-1, T-47D) than ER− breast cancer cell lines." (PMID 34131114, 2021). "Thus, ER+ breast cancer with PIK3CA mutations and higher USP35 expression may have poor survival." (PMID 34131114, 2021).
breast carcinoma (continued). "Similarly, the overall survival time of breast cancer with USP35 amplification (8.9%) or ER+ breast cancer with USP35 amplification (12.9%) was shorter than those without amplification." (PMID 34131114, 2021). "Interestingly, analysis of data in TCGA revealed that USP35 mRNA and miR-140-3p levels were inversely correlated in breast cancer (data not shown)." (PMID 34131114, 2021).
cutaneous melanoma (3 papers, 2024 to 2025). A primary melanoma arising from atypical melanocytes in the skin. "Genetic alterations of USP35 were also observed in approximately 11% of cases of cutaneous melanoma in the SKCM dataset of TCGA (n = 40/363), including copy number amplification (n = 14), multiplex alterations (n = 14), and missense mutations (n = 10)." (PMID 40016186, 2025). "Thus, our study identifies USP35 as a negative regulator of MAVS signaling, representing a potential immunosuppressive factor in cutaneous melanoma." (PMID 40016186, 2025). "Bioinformatics analysis has demonstrated a significant association between USP35 and an immunosuppressive TME, as indicated by the negative correlation between USP35 levels and CD8+ T cell infiltration in skin cutaneous melanoma." (PMID 38702734, 2024).
gastric cancer (3 papers, 2024 to 2025). A primary or metastatic malignant neoplasm involving the stomach. "This indicates that USP35 has the potential to become a diagnostic and prognostic biomarker for peritoneal metastasis of gastric cancer." (PMID 41372134, 2025). "Given the crucial role of exosome USP35 in promoting the peritoneal metastasis of gastric cancer cells, it is expected to become a potential diagnostic biomarker." (PMID 41372134, 2025). "In gastric cancer, USP35 has been implicated in Snail stabilization that appears to favor metastatic spread." (PMID 39430244, 2024). "The analysis of clinicopathological parameters suggests that high USP35 expression is positively correlated with peritoneal metastasis of gastric cancer and also predicts a poor prognosis for patients." (PMID 41372134, 2025). "In order to explore the mechanism of USP35 promoting GC progression, we used the TCGA gastric cancer dataset for GSEA and found that USP35 was positively correlated with energy metabolism and cell adhesion." (PMID 41372134, 2025). "To further examine the association between USP35 and Snail1 at the protein level, we measured the abundance of USP35 and Snail1 in various cancer cell lines, including liver, breast, prostate, and gastric cancers." (PMID 38250150, 2024).
non-small cell lung carcinoma (3 papers, 2023 to 2026). A group of at least three distinct histological types of lung cancer, including non-small cell squamous cell carcinoma, adenocarcinoma, and large cell carcinoma. "Furthermore, in non-small cell lung cancer, elevated expression of ubiquitin-specific processing protease 35 (USP35) markedly upregulates RRBP1 protein levels." (PMID 41200062, 2026). "Moreover, the expression of USP35 is positively correlated with poor prognosis of non-small cell lung cancer (NSCLC) and represses endoplasmic reticulum stress-induced apoptosis by stabilizing RRBP1." (PMID 37993419, 2023).
prostate carcinoma (3 papers, 2015 to 2023). A carcinoma that arises from epithelial cells of the prostate gland. "Our data collectively suggested the possible therapeutic implications of targeting USP35/BRPF1 as an innovative strategy to improve the overall prognosis in prostate cancer patients." (PMID 36357379, 2022). "We reported that BRPF1 is a substrate of USP35 and USP35/BRPF1 axis promotes malignant features of prostate cancer via activating the MVA pathway." (PMID 36357379, 2022). "First of all, we deleted USP35 in two prostate cancer cell lines C4-2b and PC-3 via sgRNA-mediated CRISPR/Cas9 KO technology." (PMID 36357379, 2022). "In addition, USP35 can accelerate prostate cancer growth by deubiquitinating BRPF1." (PMID 37993419, 2023). "Besides, whether USP35 regulates other biological aspects of prostate cancer remains unclear, like immune cells infiltrations or bone metastasis." (PMID 36357379, 2022). "Last of all, we are still uncertain about the relationships between USP35/BRPF1/MVA axis and castration resistance in prostate cancer." (PMID 36357379, 2022). "The results showed that the expression of USP35 was much lower in PC3 prostate cancer cells than that in non-malignant prostate epithelial cells RWPE-1." (PMID 26348204, 2015).
breast tumor (2 papers, 2015 to 2021). "Because USP35 was detected in the nucleus of ER+ breast tumor cells, we postulated that USP35 affects ERα regulated gene transcription by binding to ERE-containing DNA regions." (PMID 34131114, 2021). "We first noticed nuclear USP35 in breast tumor cells from immunohistochemistry." (PMID 34131114, 2021). "Interestingly, USP35 protein was predominately localized in the nucleus of some ER+ breast tumor samples (BC1 and BC2), and in the cytosol and nucleus of other samples (BC3)." (PMID 34131114, 2021). "USP35 nuclear staining was positively associated with ER+ breast tumors (data not shown)." (PMID 34131114, 2021). "20/22 samples showed the similar trend of miR let-7a and USP35 expression in breast tumor tissues compared with the non-cancerous tissue." (PMID 26348204, 2015).
clear cell renal cell carcinoma (2 papers, 2024 to 2025). "Silencing of USP35 leads to a reduction in NRF2 levels, thereby increasing the sensitivity of renal clear cell cancer cells to iron death induction." (PMID 39156988, 2024).
colorectal cancer (2 papers, 2023 to 2026). A primary or metastatic malignant neoplasm that affects the colon or rectum. "In this study, we for the first time investigated the role of USP35 in colorectal cancer." (PMID 36864055, 2023). "Ubiquitin-specific-processing proteases 35 (USP35) is an under-characterized deubiquitinase and its role in colorectal cancer (CRC) remains unclear." (PMID 36864055, 2023).
lentivirus infection (2 papers, 2022 to 2023). Virus diseases caused by the Lentivirus genus. "To explore whether USP35 regulates HCC development in vivo, we established stable USP35-deficient Hep3B cells through lentivirus infection and screening." (PMID 37993419, 2023). "In contrast, we generated stable USP35-overexpressing cell lines via lentivirus infection." (PMID 36357379, 2022).
acute myeloid leukemia (1 paper, 2007). Acute myeloid leukemia (AML) is a group of neoplasms arising from precursor cells committed to the myeloid cell-line differentiation. "The genes on cytoband 11q14.1, NDUFC2, ALG8 and USP35, also reside close to what appears to be a novel amplicon in acute myeloid leukemias (AML)." (PMID 17925008, 2007).
cervical cancer (1 paper, 2015). A primary or metastatic malignant neoplasm involving the cervix. "Although the expression of USP35 showed an increase in HeLa cervical cancer cells compared with that in non-malignant cervical epithelial cells H8, its expression decreased in the most cancer cell lines." (PMID 26348204, 2015).
diabetes (1 paper, 2014). "Ontological classification demonstrates that these 14 genes are associated with diabetes (ALMS1P; RAET1L; GYS1; RBM47; EFR3B), cancer (RPL27A; SPAM1; PTCH1; ZNF277; USP35; CDC86), or metabolism (C3orf15; AOC2; GOT1)." (PMID 24885560, 2014).
esophageal cancer (1 paper, 2024). A primary or metastatic malignant neoplasm involving the esophagus. "Our findings indicate that depletion of USP35 significantly enhances Cisplatin-induced cell death in esophageal cancer cell lines." (PMID 39156988, 2024). "Our findings indicate that the upregulation of NRF2 or USP35 diminishes the cytotoxic effects of Cisplatin on esophageal cancer cells." (PMID 39156988, 2024). "In conclusion, our results suggest that USP35 enhances chemotherapy resistance by deubiquitinating and stabilizing NRF2, offering a promising avenue for addressing chemoresistance in esophageal cancer through NRF2 activation." (PMID 39156988, 2024). "Our research indicates that knockdown of USP35 results in a significant elevation of NRF2 levels and enhances the sensitivity of esophageal cancer cells to chemotherapy." (PMID 39156988, 2024). "Our study identifies USP35 as a prominent candidate in the screening process and highlights its extensive investigation into the molecular mechanisms governing its regulatory role in the NRF2-ARE signaling pathway in esophageal cancer cells." (PMID 39156988, 2024). "Based on our findings, USP35 is a new type of DUB that is essential in sensitivity to chemotherapy, and may offer a potential clinical treatment for esophageal cancer." (PMID 39156988, 2024).
gastric diseases (1 paper, 2025). "Similarly, in this study, both bioinformatics analysis and IHC confirmed that with the progression of gastric diseases, the expression of USP35 increases successively in adjacent normal tissues, GC tissues, and GC tissues with peritoneal metastasis." (PMID 41372134, 2025).
hepatocellular carcinoma (1 paper, 2025). A malignant tumor that arises from hepatocytes. "Some studies have also reported that USP35 promotes the progression of hepatocellular carcinoma by protecting the key glycolytic enzyme PKM2 from ubiquitination-mediated degradation." (PMID 41372134, 2025).
lung adenocarcinoma (1 paper, 2022). A carcinoma that arises from the lung and is characterized by the presence of malignant glandular epithelial cells. "Concordantly, both RRBP1 expression and USP35 expression were found to positively correlate with poor prognoses in lung adenocarcinoma patients." (PMID 34618999, 2022). "Moreover, as the well‐characterized ER stress‐related protein GRP78 has been reported to be closely related to the prognosis of lung adenocarcinoma patients, we therefore investigated the correlation of USP35 and RRBP1 with GRP78 in the public database GEPIA." (PMID 34618999, 2022). "Finally, positive correlation between USP35 and RRBP1 in human NSCLC tissues, as well as positive correlation between USP35 or RRBP1 and shorter overall survival of lung adenocarcinoma patients was confirmed." (PMID 34618999, 2022).
malignant melanoma (1 paper, 2025). "To assess whether USP35 is associated with the tumor microenvironment in malignant melanoma, we conducted immune infiltration estimation by six algorithms, including xCell, QUANTISEQ, MCPcounter, EPIC, CIBERSORTABS, and CIBERSORT." (PMID 40016186, 2025). "In summary, Our study identified USP35 as a novel negative regulator of the MAVS-mediated type I interferon signaling pathway in malignant melanoma cells." (PMID 40016186, 2025). "To further evaluate the effectiveness of the combination therapy, we investigated the impact of USP35 knockdown on anti-tumor of oncolytic virotherapy using a mouse model of malignant melanoma." (PMID 40016186, 2025). "Further analysis of USP35 expression in the cBioPortal database showed that USP35 had the highest proportion of genomic alterations in melanoma among 26 types of tumors, gene amplification being the most frequent alteration." (PMID 40016186, 2025). "We also explored the relationship between the expression level of USP35 and the overall survival (OS) of patients with melanoma using the GEPIA database." (PMID 40016186, 2025). "To explore the expression level of USP35 in pan-cancer, we first performed bioinformatics analysis using TCGA datasets and found that USP35 was significantly up-regulated in multiple tumor tissues, including melanoma and other types of cancer." (PMID 40016186, 2025). "Knockdown of USP35 enhances the anti-tumor immunity of malignant melanoma to oncolytic virotherapy." (PMID 40016186, 2025). "Importantly, depletion of USP35 significantly enhances the anti-tumor immunity and synergizes with oncolytic virotherapy to suppress xenograft tumor growth of melanoma cells." (PMID 40016186, 2025). "In mouse malignant melanoma cell lines B16F10 and Yummer1.7, knockdown of USP35 by shRNAs, which specifically targeted USP35 mRNA, significantly enhanced VSV virus-induced expression of inflammation and antiviral-associated factors, including IFNβ, CXCL10, and ISG15." (PMID 40016186, 2025).